AGR2 (anterior gradient 2, protein disulphide isomerase family member)
Diseases named in the same sentence as AGR2 in open-access papers (continued):
Sharing a sentence is not in itself a finding about the gene and the disease.
glioblastoma (7 papers, 2019 to 2025). The most malignant astrocytic tumor (WHO grade IV). "Knocking down AGR2 using siRNA against AGR2 exon 2B in the primary cell lines had partially synergistic effects with the glioblastoma-associated drugs temozolomide and irinotecan." (PMID 36482387, 2022). "The top associated pathways in AGR2 high CNS tumors were listed, including axonal guidance signaling and glioblastoma multiforme signaling." (PMID 31247903, 2019). "Among the various genes affected, SDF1 (CXCL12) was demonstrated to induce AGR2 expression in glioblastoma cells." (PMID 38341509, 2024). "Some studies have previously analysed the role of AGR2 or GRP78 in standard glioblastoma cell lines." (PMID 36482387, 2022). "Previously, repression of AGR2 via targeting exon 7 or exon 8 in glioblastoma standard cell lines showed disruptions in the cell cycle, cell growth, migration, and cell invasion." (PMID 36482387, 2022). "We determined the levels of AGR2 protein expression in recurrent glioblastoma tissues and primary cell lines and showed its co-expression with GRP78 and several CSC markers." (PMID 36482387, 2022). "Immunofluorescence results showed, for the first time, a clear subcellular co-localisation for AGR2 with GRP78 in glioblastoma in situ and in the corresponding cell lines." (PMID 36482387, 2022). "Genomic and biological characterisations of the AGR2-expressed Jed66_GB and Jed41_GB recurrent glioblastoma tissues and cell lines showed features consistent with glioblastoma." (PMID 36482387, 2022). "In the present study, we determined the levels of the AGR2 protein expression in recurrent glioblastoma tissues and primary cell lines, and explored its co-expression with GRP78 and several CSC markers." (PMID 36482387, 2022). "Overexpressed AGR2 was also demonstrated to contribute to growth and angiogenesis of glioblastoma in vitro and in tumor xenografts." (PMID 32493835, 2020). "For instance, in glioblastoma, AGR2 was increased by HIF1, which led to enhanced migration and tube formation capabilities of cells in vitro and increased growth and vascularity of tumor xenografts in vivo." (PMID 32322663, 2020). "A high expression of AGR2 was also detected in the glioblastoma cell lines T98G, A172, U87 and U251." (PMID 31247903, 2019). "In CNS tumors, the evaluation of AGR2 expression levels in the glioblastomas (GBM) U87 and LN18 cell lines revealed an up-regulated AGR2." (PMID 31247903, 2019). "However, this meta-analysis did not include central nervous system (CNS) tumors, even though the AGR2 overexpression had been detected in CNS tumors, including glioblastoma multiforme (GBM) and meningiomas." (PMID 31247903, 2019). "An investigation of glioblastoma multiforme tumor (GBM) cells showed that AGR2 expression was regulated by HIF-1α and directed glioblastoma cell growth and the vascularity of tumors." (PMID 37175601, 2023). "Hence, we investigated the role of AGR2 in drug-resistant recurrent glioblastoma cells." (PMID 36482387, 2022). "In glioblastoma (GBM), AGR2 is significantly overexpressed, disrupting cellular homeostasis and fostering malignant transformation." (PMID 41179304, 2025). "This study focused on understanding the importance of the metastatic-related biomarker AGR2 and the UPR protein GRP78 in glioblastoma tissues and corresponding primary cell lines, with particular attention paid to CSCs and drug resistance." (PMID 36482387, 2022). "In conclusion, the data demonstrate that AGR2 and GRP78 are highly expressed in glioblastoma CSCs and drug-resistant cells in situ and in vitro." (PMID 36482387, 2022). "To date, the contribution of GRP78 and AGR2 to drug resistance in CSCs of glioblastoma tissues and primary cell lines has not been clarified." (PMID 36482387, 2022). "The finding that both AGR2 and GRP78 proteins are colocalised with CSC markers in the same tissues as well as in the corresponding cell lines suggests a functional interaction of AGR2 and GRP78 in glioblastoma-CSCs." (PMID 36482387, 2022).
glioblastoma (continued). "This suggests that the presence of AGR2 is critical for glioblastoma cell survival, regardless of drug type." (PMID 36482387, 2022).
prostate tumor (7 papers, 2014 to 2019). "In prostate tumor glands in vivo, the stromal cells adjacent to the AGR2+ cancer cells are CD90+ cancer-associated (CP) stromal cells, which differ from NP stromal cells in overall gene expression." (PMID 27283903, 2016). "The splice variants AGR2 SV-C, -E, -F, -G and -H showed varying levels of expression among the different cell lines while AGR2 SV-C was mainly expressed at low levels only in prostate tumor cell lines." (PMID 25237833, 2014). "Using antibodies P1G4 (IgG1) and P3A5 (IgG2a) that were generated against the AGR2 protein, a high expression of AGR2 was revealed in prostate tumor specimen tissues and cultured cells." (PMID 31247903, 2019). "Here only AGR2wt and AGR2 SV-H levels were found to be significantly different between benign and prostate tumor." (PMID 25237833, 2014). "The overexpression of AGR2 was observed in several tumor types, which supports the hypothesis of AGR2 be an oncogene, but the downregulation of this gene also was observed in prostate tumors, ovarian, colorectal, and pancreas." (PMID 29845750, 2018). "In addition, the observation of faint AGR2 staining of the stroma (in frozen sections) next to the prostate tumor glands could be used to indicate that AGR2 was secreted." (PMID 26894971, 2016).
squamous cell carcinoma (7 papers, 2015 to 2025). A carcinoma arising from squamous epithelial cells. "Effect of KAI1, MACC1, and AGR2 on postoperative survival time in patients with squamous cell carcinoma of the uterine cervix." (PMID 41239615, 2025). "That adenocarcinomas are more commonly positive than squamous cell carcinomas reflects the limited AGR2 expression in normal squamous epithelium." (PMID 39533806, 2024). "AGR2 positivity was slightly less common in neuroendocrine neoplasms (20.0%–100%) and in squamous cell carcinoma (46.4%–77.3%)." (PMID 39533806, 2024). "As a general feature, squamous cell carcinomas expressed AGR2 and AGR3 at a much lower level than adenocarcinomas (compare, for instance, LUAD with LUSC, ESCA with HNSC, CESC with UCEC)." (PMID 35857928, 2022). "When segregated by tumor types, high AGR2 expression was more pronounced in adenocarcinoma: 62 % for grade 1, 62 % for grade 2, and 51 % for grade 3; whereas in squamous carcinoma: 19 % for grade 1, 20 % for grade 2, and 31 % for grade 3." (PMID 26445321, 2015). "In esophageal cancer, AGR2 can be used to improve distinguishing adenocarcinoma (99 % positive) from squamous cell carcinoma (37 % positive, typically in focal areas) in some circumstances." (PMID 26445321, 2015). "Besides differential expression in tumor grades, AGR2 expression is found preferentially in the adenocarcinoma type than the squamous cell carcinoma type of NSCLC." (PMID 26445321, 2015). "However, very few of them considered AGR2 roles in squamous cell carcinoma." (PMID 36327302, 2022). "To determine whether over-expression of AGR2 was related to high-grade squamous cell carcinoma in mice, we performed AGR2 immunohistochemistry and found that AGR2 was located mostly in the membrane and cytoplasm of the cancer cell of Tgfbr1 cKO mice and Tgfbr1/Pten 2cKO mice (n = 5, respectively)." (PMID 25871396, 2015). "The expression of AGR2 and BRD7 was cell type-dependent; AGR2 was more highly expressed in adeno/adenosquamous carcinoma, and BRD 7 expression was more prominent in squamous cell carcinoma (p < 0.001 and p = 0.004, respectively)." (PMID 30406031, 2018). "AGR2 positivity was slightly less common in squamous cell carcinomas (46.4%–77.3%) and mainly absent in mesenchymal and lymphoid tumors." (PMID 39533806, 2024). "AGR2 may affect cell apoptosis, invasion, proliferation, metastasis, and the EMT signaling pathway in squamous cell carcinoma." (PMID 36327302, 2022). "AGR2 did not predict survival differences when patients were divided by histology (adenocarcinoma vs. squamous carcinoma) or by smoking status." (PMID 26445321, 2015).
Crohn disease (6 papers, 2018 to 2024). A gastrointestinal disorder characterized by chronic inflammation involving all layers of the intestinal wall, noncaseating granulomas affecting the intestinal wall and regional lymph nodes, and transmural fibrosis. "Polymorphisms in the AGR2 gene have been associated with increased risk of Ulcerative colitis and Crohn’s disease and Agr2-/- mice lack an inner mucus layer in their GI tract." (PMID 38177501, 2024). "Thus, low levels of TMED2 are associated with quiescent Crohn's disease as a consequence of fewer AGR2 dimers, causing some inflammation." (PMID 31878985, 2019). "Deletion of AGR2 in mice resulted in ER stress in the intestinal epithelium, disrupted paneth cell homeostasis, and the animals developed Crohn’s disease-like granulomatous ileocolitis." (PMID 32630206, 2020). "Herein, we have identified that a normally endoplasmic reticulum resident protein, member of the protein disulfide isomerase family, AGR2, exhibits tightly regulated secretion mechanisms that are perturbed in Crohn's disease." (PMID 31040128, 2019). "We also demonstrate that in IBD and specifically in Crohn's disease, the levels of AGR2 dimerization modulators are selectively deregulated, and this correlates with severity of disease." (PMID 31040128, 2019). "Interestingly, TMED2 was recently reported to play a role in Crohn's disease through the regulation of the dimeric state of AGR2 (anterior gradient 2)." (PMID 31878985, 2019). "Consequently, AGR2 knockout mice spontaneously develop severe ileocolitis that histopathologically resembles human Crohn’s disease." (PMID 29796176, 2018).
lymph node metastasis (6 papers, 2014 to 2025). "High levels of AGR2 were associated with the T category, pathological grade and lymph node metastasis of HNSCC." (PMID 25871396, 2015). "Surprisingly, our data demonstrated overexpression of AGR2 was associated with lymph node metastasis in NPC tissues as well." (PMID 24717913, 2014). "AGR2 protein expression correlated with high grade head and neck SCC, with T status and with lymph node metastasis." (PMID 32733958, 2020). "Multivariate COX regression analysis showed that the positive expression of KAI1, MACC1, and AGR2, TNM stage and lymph node metastasis stage in clinicopathological factors were independent prognostic factors for the OS time of patients with cervical squamous cell carcinoma (P < .05)." (PMID 41239615, 2025).
bladder cancer (5 papers, 2012 to 2024). "Thus, in a majority of analyzed bladder cancer cases, malignant transformation was accompanied by a loss of urothelial AGR2." (PMID 26894971, 2016). "Some cancer types presented more mutations than others: skin cutaneous melanomas and endometrial carcinomas for AGR2, and the same plus stomach and bladder carcinomas for AGR3." (PMID 35857928, 2022). "Another mode of action that could be behind ETV’s capacity to decrease the viability of bladder cancer cells is the inhibition of the human anterior gradient protein 2 homolog (AGR2)." (PMID 38540260, 2024). "The detection of AGR2 in the urine of a subset of bladder cancer patients indicates that AGR2 could be secreted by urothelial carcinoma cells." (PMID 26894971, 2016). "AGR2 expression in bladder cancer was examined in a cohort of patients with lymph node involvement." (PMID 26894971, 2016). "The drug’s ability to inhibit casein kinase 1 ε (CK1ε) and the human anterior gradient protein 2 homolog (AGR2) may contribute to its efficacy in inducing cell cycle arrest and apoptosis in bladder cancer cells." (PMID 38540260, 2024). "Unlike the prostate and pancreas where AGR2 is up-regulated in cancer cells compared to normal cells, AGR2 is down-regulated in a majority of bladder cancer cells compared to normal bladder cells." (PMID 26894971, 2016).
esophageal squamous cell carcinoma (5 papers, 2022 to 2025). Esophageal squamous cell carcinoma (ESCC) is a type of esophageal carcinoma (EC) that can affect any part of the esophagus, but is usually located in the upper or middle third. "In esophageal squamous cell carcinoma, studies have found the expression of the adenocarcinoma marker AGR2, which reflects the abnormal protein expression caused by tumor heterogeneity." (PMID 41333217, 2025).
hepatocellular carcinoma (5 papers, 2020 to 2024). A malignant tumor that arises from hepatocytes. "In conclusion, though the precise role of AGR2 in cancer is not fully understood, it has been implicated in cancer invasion and metastasis across several cancer types, including hepatocellular carcinoma." (PMID 39062458, 2024). "While the role of AGR2 in hepatocellular carcinoma and cholangiocarcinoma remains to be fully elucidated, future research focusing on immunotherapy and exploring the link between AGR2 and these specific cancers is warranted to advance clinical applications in cancer treatment." (PMID 39062458, 2024). "Additionally, AGR2 downregulation led to a significant decrease in lipid accumulation and TG/TC levels in hepatocellular carcinoma Huh7 cells." (PMID 33767592, 2021).
liver cancer (5 papers, 2020 to 2025). An epithelial or non-epithelial malignant neoplasm that arises from the liver. "The same study showed that chemically-induced ER stress caused upregulation of AGR2 in liver cancer cells, suggesting that AGR2 is important in ER regulation and quality control." (PMID 33005802, 2020). "Interestingly, anterior gradient 2 (AGR2) was identified as a major gene highly correlated with survival rate and sorafenib resistance in liver cancer, but its associated mechanism and physiological significance have not been well elucidated." (PMID 36899352, 2023). "In the present study, we found that AGR2 was highly correlated with overall and recurrence-free survival rates and with several clinical parameters in liver cancer." (PMID 36899352, 2023). "Events of abnormal AGR2 gene splicing, which are unique in liver cancer, were however expressed at very low levels." (PMID 33005802, 2020). "AGR2 is a known unfavourable prognostic marker in renal and liver cancer and OAC." (PMID 40073002, 2025). "Interestingly, AGR2 is the major gene highly correlated with the survival rate and sorafenib resistance in liver cancer; however, the relationship between AGR2 and sorafenib treatment in HCC has not been demonstrated." (PMID 36899352, 2023). "Moreover, AGR2 is highly expressed in numerous cancer types, including liver cancer." (PMID 36899352, 2023).
melanoma (5 papers, 2022 to 2026). A malignant, usually aggressive tumor composed of atypical, neoplastic melanocytes. "We confirmed that JUP and AGR2 were associated with unfavourable prognosis of melanoma by KM curves, and that AGR2 was associated with higher T stage and deeper Breslow depth." (PMID 37924160, 2023). "Our results suggest the presence of Plakoglobin (JUP)/Anterior Gradient 2 (AGR2)/LY6/PLAUR Domain Containing 3 (LYPD3) pro-oncogenic signaling in melanoma." (PMID 37924160, 2023). "We stained and visualized the cytoskeleton using phalloidin and found that JUP/AGR2/LYPD3 can help melanoma cells form pseudopodia." (PMID 37924160, 2023). "In the present study, we demonstrated that upregulation of JUP/AGR2/LYPD3 signaling promotes melanoma cytoskeleton remodeling and stimulates the formation of new pseudopods." (PMID 37924160, 2023). "It was shown that hyperactivation of the JUP/AGR2/LYPD3 signaling axis contributes to the regulation of melanoma cell stemness and promotes glycolysis through a Glucose Transporter Type 1 (GLUT1)-dependent pathway." (PMID 37924160, 2023). "We demonstrated that JUP regulates Anterior Gradient 2 (AGR2)/LY6/PLAUR Domain Containing 3 (LYPD3) to maintain melanoma stemness and promotes glycolysis." (PMID 37924160, 2023). "In the MEL-JUSO melanoma cell line, the frameshift P38fs*37 AGR2 variation is accompanied by the lowest AGR2 mRNA expression in melanoma cell lines, but only in the GDSC database." (PMID 35857928, 2022). "The JUP/AGR2/LYPD3 signaling axis plays an important role in the malignant features of melanoma." (PMID 37924160, 2023). "This study extends the biological significance of the JUP/AGR2/LYPD3 signaling axis to melanoma." (PMID 37924160, 2023). "Considering that JUP is a homologue of β-catenin and is closely related to β-catenin in many cases to concertedly regulate cell fate, we speculate that there may be a mechanism of JUP/AGR2/LYPD3 signaling regulation in melanoma." (PMID 37924160, 2023). "We confirmed that the JUP/AGR2/LYPD3 signaling axis promotes F-actin expression, remodels the cytoskeleton and confers a robust invasive phenotype to melanoma cells." (PMID 37924160, 2023). "Our findings suggest that the JUP/AGR2/LYPD3 signaling axis plays an important role in melanoma, but its in-depth mechanism of action is still lacking." (PMID 37924160, 2023). "AGR2 staining was only rarely seen in adrenocortical tumors (4.3%–9.3%) and in renal cell carcinoma (7.8%–26.5%), and mainly absent in melanoma, seminoma, embryonal carcinoma, adrenocortical neoplasms, tumors of the hematopoietic and lymphoid tissues, as well as mesenchymal tumors." (PMID 39533806, 2024).
pancreatic adenocarcinoma (5 papers, 2007 to 2024). "Next, we compared AGR2 mRNA expression in normal pancreas and pancreatic adenocarcinoma using the GEPIA online tool." (PMID 39727484, 2024). "It has recently been reported that mouse AGR2 acts via the orphan membrane receptor C4.4A in models of pancreatic adenocarcinoma." (PMID 27100463, 2016). "AREG was chosen based on previous gene expression studies that identified enhanced Anterior Gradient 2 (AGR2) expression in all pancreatic adenocarcinomas." (PMID 22333441, 2012). "AREG's discovery as a potential cyst fluid biomarker arose from observations of increased Anterior Gradient 2 (AGR2) gene expression among pancreatic adenocarcinomas." (PMID 22333441, 2012). "Enhanced AGR2 expression and activated EGFR signaling is present in all pancreatic adenocarcinomas, chronic pancreatitis, and premalignant pancreatic intraepithelial neoplasias." (PMID 27764193, 2016).